ZNF880 (zinc finger protein 880)
Tractability: PROTAC: ubiquitination databases record sites on it.
Gene: Protein-coding gene on chromosome 19 (52,369,917 to 52,393,738, forward strand). Ensembl gene ENSG00000221923.
Subcellular location (Human Protein Atlas): Nucleoli fibrillar center; Intermediate filaments; Nucleoplasm
Gene Ontology:
Molecular function: DNA-binding transcription factor activity, RNA polymerase II-specific; RNA polymerase II cis-regulatory region sequence-specific DNA binding
Biological process: regulation of transcription by RNA polymerase II; regulation of DNA-templated transcription
Cellular component: nucleus
Genetic constraint (gnomAD): Loss-of-function variants: 12 observed, 12.69 expected, observed/expected ratio (o/e) 0.95, 90% interval 0.6 to 1.52. The upper end of that interval is the gene's LOEUF score, 1.52, which puts it in group 6 of 6, group 1 being the genes least tolerant of losing a copy. Missense variants: 601 observed, 664.58 expected, observed/expected ratio (o/e) 0.9, 90% interval 0.85 to 0.97. Synonymous variants: 210 observed, 228.1 expected, observed/expected ratio (o/e) 0.92, 90% interval 0.82 to 1.03.
Homologues: Orthologues: chimpanzee ZNF880 (97% identical). Paralogues in human: ZNF528 (69% identical), ZNF83 (51% identical), ZNF841 (42% identical), ZNF534 (41% identical), ZNF28 (40% identical), ZNF836 (40% identical), ZNF658 (39% identical), ZNF85 (39% identical), ZNF546 (39% identical), ZNF595 (39% identical), ZNF33B (39% identical), ZNF724 (39% identical), and 164 more.
Diseases named in the same sentence as ZNF880 in open-access papers:
ZNF880 is named in the same sentence as 10 diseases in open-access papers, as found by Europe PMC text mining. Sharing a sentence is not in itself a finding about the gene and the disease. The quoted sentences say what the papers report.
colorectal cancer (2 papers, 2022 to 2023). A primary or metastatic malignant neoplasm that affects the colon or rectum. "Functional studies using colorectal cancer models along with ChIP-seq to study the target genes and binding sites of ZNF880 will contribute to a comprehensive understanding of ZNF880's function and regulatory mechanism in colorectal cancer." (PMID 37370088, 2023). "In this study, ZNF880 was significantly associated with overall survival (OS) and disease-free survival (DFS) in colorectal carcinoma (CRC) patients." (PMID 37370088, 2023). "We have observed a concurrent downregulation of ZNF880 and upregulation of CDK1 in colorectal cancer samples, suggesting a potential direct or indirect regulatory relationship between the two." (PMID 37370088, 2023). "In contrast, ZNF880 and ZFP28 were found upregulated in colorectal cancer and melanoma, respectively." (PMID 36547193, 2022). "In summary, ZNF880 may regulate CDK1 expression levels through transcriptional repression, thereby impacting the progression of colorectal cancer." (PMID 37370088, 2023).
colon adenocarcinoma (1 paper, 2023). "Combined with Colon adenocarcinoma (COAD) and Rectum adenocarcinoma (READ) data collection in the TCGA database, we found that ZNF880 was significantly down-regulated in CRC." (PMID 37370088, 2023).
endometrial carcinoma (1 paper, 2023). A malignant tumor arising from the epithelium that lines the cavity of the uterine body. "The results show that ZNF880 has the highest degree of variation in Endometrial Carcinoma and CRC." (PMID 37370088, 2023).
rectal cancer (1 paper, 2023). A primary or metastatic malignant neoplasm that affects the rectum. "Little is known about ZNF880 except that it has an unclear role in breast and rectal cancer, and additional experiments are necessary to elucidate its role in EDMD." (PMID 36282542, 2023).
cancer (3 papers, 2020 to 2023). A tumor composed of atypical neoplastic, often pleomorphic cells that invade other tissues. "ZNF880 has the potential to become a new target for anti-cancer therapy or a biomarker for clinical patient management." (PMID 37370088, 2023). "In order to evaluate the mRNA expression patterns of ZNF880 in different cancer types, we analyzed the differences in the expression of ZNF880 in cancer tissues and normal tissues in the data of more than 23 cancer types." (PMID 37370088, 2023). "Among them, ZNF880 was down-regulated in more than 7 cancer types, but only up-regulated in two cancers." (PMID 37370088, 2023). "Overall, ZNF880 may exhibit tumor suppressor activity in most cancers." (PMID 37370088, 2023). "In order to evaluate the sequence variation of ZNF880 in CRC, we first counted the variation of ZNF880 in pan-cancer." (PMID 37370088, 2023).
tumor (3 papers, 2020 to 2023). "To further determine the role of ZNF880 in tumor immunity, we analyzed the correlation between ZNF880 and 16 immune cell marker genes." (PMID 37370088, 2023). "The results showed that ZNF880 was significantly downregulated at the protein level in the tumor tissues of 3 CRC patients." (PMID 37370088, 2023). "Based on the UALCAN database, we observed a significant downregulation of ZFP28, ZNF132, ZNF418, ZNF426, ZNF540, and ZNF880 expression levels in primary tumor tissues compared to normal tissues." (PMID 36547193, 2022). "First, we found that the expression level of most ZNFs (apart from ZNF880) depended on tumor location." (PMID 36547193, 2022). "Subsequently, the expression of ZNF880 in CRC tumor staging was analyzed, and the results showed that ZNF880 showed an up-regulated expression trend in tumor staging, and overall the expression was significantly down-regulated in the initial stage of tumorigenesis." (PMID 37370088, 2023). "The GSE14333 dataset was used as the validation cohort to further validate the hypothesis that ZNF880 may function as a possible tumor suppressor gene in CRC in this study." (PMID 37370088, 2023). "The low expression of ZNF880 leads to a decrease in the expression of REC8 and thus limits the tumor suppressor activity of REC8." (PMID 37370088, 2023). "We analyzed the correlation between the expression of ZNF880 in the TIMER database and the four types of tumor infiltrating immune cells, and the expression of ZNF880 showed a significant negative correlation with tumor (COAD) purity (r = − 0.149, p = 2.66e − 03)." (PMID 37370088, 2023).
ZNF880 also shares sentences with these, for which no sentence is quoted: breast carcinoma (1 paper); colon cancer (1); melanoma (1); rectum adenocarcinoma (1).